MFN1 (mitofusin 1)
Diseases named in the same sentence as MFN1 in open-access papers (continued):
Sharing a sentence is not in itself a finding about the gene and the disease.
lung carcinoma (7 papers, 2018 to 2025). "Patients with early, operable lung cancer exhibited significantly lower levels of MFN1 protein compared to patients with advanced, metastatic lung cancer, according to the AJCC classification." (PMID 39199596, 2024). "In blood serum, in the group of lung cancer patients, the level of MFN1 protein was significantly higher (p < 0.01; Mann–Whitney U test) and the FIS1 protein level was significantly lower compared to the healthy control group (p < 0.001; Mann–Whitney U test)." (PMID 39199596, 2024). "Patients with early, operable lung cancer had significantly lower levels of MFN1 immunoexpression compared to patients with advanced, metastatic lung cancer (p < 0.05; UMW test)." (PMID 39199596, 2024). "Fission was upregulated in HCC due to elevated Drp1 and depressed Mfn1 expression, which is consistent with findings in lung cancer, albeit in HCC the dysregulated mitofusin was Mfn1." (PMID 37508561, 2023). "Here, we found that copy number amplification of OPA1 and MFN1 were co-occurring and synergistically activated in tumor epithelial cells in lung cancer tissues." (PMID 36573240, 2022). "Here, we found that copy number amplification of OPA1 and MFN1 were co-occurring and synergistically activated in lung cancer tissues." (PMID 36573240, 2022). "Additionally, research has shown concurrent amplification of OPA1 and MFN1 copy numbers, synergistically activated in tumor epithelial cells in lung cancer tissues." (PMID 38911373, 2024). "Moreover, significant correlations between the abnormal expressions of mitochondrial dynamic proteins of DRP1 and MFN1 and the prognosis of patients have also been reported in liver and lung cancers." (PMID 33317572, 2020). "In our study, patients with early, operable lung cancer (regardless of the histopathological type) had a significantly lower level of expression of the MFN1 fusion protein compared to patients with advanced, metastatic lung cancer." (PMID 39199596, 2024).
osteosarcoma (7 papers, 2013 to 2025). A usually aggressive malignant bone-forming mesenchymal neoplasm, predominantly affecting adolescents and young adults. "MFN1 overexpression was also shown to induce apoptotic cell death of osteosarcoma cells, reducing malignancy, while the microRNA miR-19b, predicted to downregulate MFN1, had the opposite effect." (PMID 33072754, 2020). "In the present study, we further confirmed that Tan IIA indeed reduced the levels of Mfn-1, Mfn-2 and Opa-1 and increased the levels of Drp-1 in both osteosarcoma 143B cells and 143B cell xenograft mice." (PMID 28106052, 2017). "Enlarged but functional mitochondria were also observed in several osteosarcoma, lung, and renal cancer cells after exposure to hypoxia; in contrast to fluid influx, this was due to MFN1-mediated abnormal fusion events and protected hypoxic cells against apoptosis." (PMID 33520711, 2020). "Conversely, the expression of fusion-related proteins was mostly unaffected after treatment, with one exception: mitofusin-1 (MFN1) was down-regulated in response to topotecan in NSTS-11 rhabdomyosarcoma cells and both osteosarcoma cell lines." (PMID 39643272, 2025). "Mitofusin 1 (Mfn1) when phosphorylated by ERK1/2 inhibits mitochondrial fusion while mitofusin 2 (Mfn2) when phosphorylated by JNK becomes a substrate for the proteasome and promotes the fragmentation of mitochondria in human osteosarcoma cells." (PMID 33498615, 2021). "In this study, the parental osteosarcoma cells harboring haplogroup X, after bile acid treatment, had different MMP, higher mtDNA copy number, different ROS production, higher cellular apoptosis and lower Mfn1 and Mfn 2 expression levels." (PMID 23966875, 2013).
ovarian carcinoma (6 papers, 2020 to 2025). A malignant neoplasm originating from the surface ovarian epithelium. "recently reported that TRAF3 interacts with the mitochondrial fusion protein mitofusin-1 (MFN1) in ovarian cancer cells, which is enhanced upon TLR4 signaling induced by Selene nanoparticles." (PMID 36776285, 2023). "To examine the role of mitochondrial dynamics in DDP resistance in ovarian cancer cells, we first examined the expression of mitochondrial dynamics-related proteins including MFN1, MFN2, DRP1, and OPA1 in SKOV3 and SKOV3/DDP cells." (PMID 35003356, 2021). "In contrast, a new reports identified that hypoxia-induced ROS triggers mitochondrial fission by down-regulating phosphorylated Drp1 (Ser637) and Mfn1 expression levels in ovarian cancer cells, thereby inducing cisplatin resistance." (PMID 34868997, 2021). "Specifically, MFN1 expression levels were downregulated in SKOV3 and PA1 ovarian cancer cell lines, upon hypoxia, which caused reactive oxygen species (ROS) production, leading to an increased fission-to-fusion ratio of mitochondria." (PMID 33233365, 2020). "Under hypoxic conditions, ovarian cancer cells were found to undergo metabolic reprogramming and activate MFN1-mediated mitochondrial fission, ultimately leading to reduced production of reactive oxygen species (ROS) within the mitochondria and an increase in the survival of such cells." (PMID 38038814, 2023). "Mitofusin 1 (MFN1), a protein localized in the mitochondrial outer membrane, is known to regulate mitochondrial dynamics and play a vital role in ovarian cancer progression via modulation of mitochondrial dynamics, metabolism, and response to chemotherapy." (PMID 38038814, 2023).
Atrophy (5 papers, 2021 to 2024). Any weakening or degeneration, especially through lack of use. "Mitochondrial fusion is regulated by mitofusin 1 (MFN1), mitofusin 2 (MFN2), and optic atrophy (OPA1)." (PMID 33716776, 2021).
atherosclerosis (4 papers, 2021 to 2026). A disease characterized by the build-up of fatty material and calcium deposition in the arterial wall resulting in partial or complete occlusion of the arterial lumen. "Furthermore, to investigate the involvement of MAMs in atherosclerosis pathogenesis, we examined the expression of three core MAMs-related molecules—Mitofusin 1 (MFN1), Mitofusin 2 (MFN2), and Mitochondrial Fission 1 (Fis1)—in the same PBMC samples." (PMID 41614904, 2026). "The mitochondrial fusion proteins MFN1 and MFN2 maintain the mitochondrial network and protect endothelial cell function by initiating OMM fusion.Reduced expression of MFN1 and MFN2 leads to endothelial dysfunction and inhibition of VSMC proliferation, promoting the progression of atherosclerosis." (PMID 40093324, 2025). "Mitochondrial-localized AIBP is related to MFN1 and MFN2 through its N-terminal domain and regulates their ubiquitination, thereby enhancing mitochondrial autophagy and participating in mitochondrial quality control, protecting macrophages from cell death in atherosclerosis." (PMID 34336087, 2021).
Charcot-Marie-Tooth disease (4 papers, 2016 to 2023). An inherited degenerative disorder involving the peripheral nerves. "Defective mitochondrial fusion causes an accumulation of neutral lipids within lipid droplets in both mitofusin 1 knockout cells and fibroblasts from Charcot-Marie-Tooth disease (CMT) type 2A patients." (PMID 32957716, 2020). "Mice deficient in Mfn1, Mfn2, and OPA1 are all embryonic lethal and in humans, mutations in OPA1 are linked to hereditary blindness, and Mfn2 mutations are known to cause Charcot-Marie-Tooth disease." (PMID 29062571, 2017). "Knockout mice of Mfn1, Mfn2, and OPA1 are all embryonic lethal and mutations in OPA1 in humans are associated with hereditary blindness, while Mfn2 mutations are the cause of Charcot-Marie-Tooth disease." (PMID 28097021, 2016).
female infertility (4 papers, 2019 to 2025). Diminished or absent ability of a female to achieve conception. "Oocyte-specific MFN1 deletion causes female infertility due to defective oocyte maturation and follicular development." (PMID 39598305, 2024). "First, we uncovered that oocyte specific deletion of Mfn1 results in female infertility due to defective oocyte maturation and follicular development." (PMID 31332167, 2019). "In addition to DRP1, several studies demonstrated that the conditional knock-out of mitofusin 1 or 2 (MFN1 or MFN2) leads to male or female infertility in mice models." (PMID 35493072, 2022).
male infertility (4 papers, 2021 to 2024). The inability of the male to effect fertilization of an ovum after a specified period of unprotected intercourse. "Map7d1 facilitates microtubule stabilization and Mfn1 deficiency leads to defects in mitochondrial activity and male infertility." (PMID 38470475, 2024). "We previously revealed that either Mfn1 or Mfn2 conditional knockout in early germ cells resulted in male infertility." (PMID 34948301, 2021). "Another study, relating to testicular damage caused by Cadmium (Cd) also found that an intraperitoneal injection of Cd into rats resulted in reproductive toxicity, including poor semen quality, male infertility, and reduced expression levels of mRNA for both Mfn1 and Mfn2." (PMID 35725948, 2022). "However, the intraperitoneal injection of vitamin E improved the mRNA expression levels of Mfn1 and Mfn2, thus improving Cd-induced poor semen quality and male infertility." (PMID 35725948, 2022).
neuroblastoma (4 papers, 2019 to 2025). Neuroblastoma (NB) is the most common solid, extracranial childhood tumor. "Mitochondrial elongation due to mitochondrial protein rearrangement is helpful to resist cisplatin-induced treatment in neuroblastoma cells while silencing of MFN1 inhibits mitochondrial fusion but increases cisplatin sensitivity." (PMID 32974209, 2020). "Similarly, MFN1/2 upregulated in L1210 cells was responsible for the resistance to cisplatin treatment, whereas the inhibition of mitochondrial fusion by silencing of MFNs sensitized neuroblastoma cells to cisplatin." (PMID 32974209, 2020). "The potential mechanism of this type of change is increased mitofusin 1 (MFN1) and OPA1, which was confirmed by the authors in an in vitro model for rat cortical neurons and SH-SY5Y rat neuroblastoma cells exposed to gp120." (PMID 34685718, 2021). "Other studies have shown that expression of APP695 in M17 neuroblastoma cell line showed an increase in the level of mitochondrial fission 1 protein (FIS1), a fission protein, and decreased levels of mitofusin 1 (MFN1) and OPA1, proteins involved in fusion." (PMID 31824296, 2019).
prostate carcinoma (4 papers, 2016 to 2023). A carcinoma that arises from epithelial cells of the prostate gland. "Furthermore MITOL is required for degradation of mitochondrial fusion protein Mfn1 in LNCaP prostate cancer cells treated with CGP37157 (CGP), an inhibitor of mitochondrial calcium efflux, and resulted in mitochondrial fission." (PMID 27444773, 2016). "Moreover, MFN1 depletion in prostate cancer cells increased the cell death response to CGP." (PMID 31156446, 2019). "Induction of cell death in prostate cancer cells with CGP led to ubiquitylation and degradation of MFN1." (PMID 31156446, 2019).
glaucoma (3 papers, 2009 to 2024). Increased pressure in the eyeball due to obstruction of the outflow of aqueous humor. "Regarding the MFN1 gene, we also detected another variant (p.E701X) in a 68-year-old patient with severe glaucoma." (PMID 38241218, 2024). "Those rare variants are located in CYP1B1, SIX6, CARD10, MFN1, OPTC, OPTN, and WDR36 glaucoma-related genes." (PMID 38241218, 2024). "The objective of this study was to investigate association of several genes that have not been subject to an association study with glaucoma cases so far but might be functionally linked to glaucoma pathogenesis (RDX, SNX16, MFN1, MFN2, PARL, SOD2)." (PMID 19754948, 2009). "Besides, we found one patient with severe glaucoma and two VUS in CARD10 and MFN1." (PMID 38241218, 2024).
glioma (3 papers, 2022 to 2024). A benign or malignant brain and spinal cord tumor that arises from glial cells (astrocytes, oligodendrocytes, ependymal cells). "YME1L silencing or KO resulted in reduction of TIMM44-dependent mitochondrial genes, including Opa1, Mfn1 and Mfn2, in P1 glioma cells." (PMID 36438483, 2022). "TSPO-deficient mouse glioma cells also showed a marked reduction in MFN1 levels and no change in DRP1 protein expression." (PMID 39684592, 2024). "Opa1, Mfn1 and Mfn2, TIMM44-dependent mitochondrial genes, were increased in TIMM44-overexpressed P1 glioma cells." (PMID 36438483, 2022). "mRNA expression of TIMM44-dependent mitochondrial genes, including Opa1, Mfn1 and Mfn225, were dramatically decreased with TIMM44 silencing or KO in P1 glioma cells." (PMID 36438483, 2022).
Huntington disease (3 papers, 2018 to 2025). Huntington disease (HD) is a rare neurodegenerative disorder of the central nervous system characterized by unwanted choreatic movements, behavioral and psychiatric disturbances and dementia. "Additionally, research has indicated that in the brains of patients with Huntington’s disease (HD) postmortem, there is an increased expression of Drp1 and FIS1, while the expressions of Mfn1, Mfn2, and OPA1 are reduced." (PMID 41178992, 2025). "In addition, tissues from Alzheimer’s disease (AD) and Huntington's disease (HD) patients demonstrated increased expression of DRP1 and FIS1, and decreased expression of MFN1, MFN2 and OPA1, indicating that an impairment on mitochondrial dynamics are associated with AD and HD." (PMID 33782711, 2021).
invasive breast carcinoma (3 papers, 2016 to 2021). A carcinoma that infiltrates the breast parenchyma. "DRP1 was shown to be upregulated in invasive breast carcinomas, lymph node metastases, and cell lines prone to metastasis, and reducing fission (by silencing DRP1 or overexpressing MFN1) inhibited metastasis formation." (PMID 34069047, 2021). "Similarly, in human invasive breast carcinoma, mitochondria were more fragmented in metastatic than in nonmetastatic cells, due to upregulation of DRP1 and downregulation of MFN1." (PMID 34069047, 2021). "Indeed, invasive breast carcinomas and metastases express higher levels of DRP1 and lower levels of MFN1 compared to non-metastatic breast tumors." (PMID 33572276, 2021).
ischemic stroke (3 papers, 2022 to 2025). A stroke disorder caused by obstruction of blood flow to the brain, due to thrombotic (local blood clot formation) or embolic (due to a blood clot or other material traveling from another site) event. "Discussion: Our results revealed that NBP is a novel mitochondrial fusion promoter in protecting against ischemic stroke through the AMPK-mediated Mfn1." (PMID 38455957, 2024). "Our results have revealed that NBP is a novel mitochondrial fusion promoter in protecting against ischemic stroke through the AMPK-mediated Mfn1." (PMID 38455957, 2024). "In consistent with previous studies, the present study showed that the expression levels of MFN1 and MFN2 were significantly elevated after silencing ATF3 in OGD/R-treated cells and ischemic stroke rats, suggesting the protective effect of silencing ATF3 on mitochondrial homeostasis." (PMID 40621504, 2025).
metabolic syndrome (3 papers, 2019 to 2025). A cluster of metabolic risk factors for CARDIOVASCULAR DISEASES and TYPE 2 DIABETES MELLITUS. "Similarly, dapagliflozin normalizes the Mfn1/Mfn2 ratio in the rat model of metabolic syndrome, thereby suppressing prolonged ventricular repolarization." (PMID 31970162, 2019). "However, this acute exercise performed by metabolic syndrome patients reduces the gene expression of CoxIV and Tfam and maintains the basal expression of MitoND5, UCP3, HO1, MnSOD, GPx, CAT, Mfn1, Mfn2, Nrf2 and PGC1α." (PMID 34198661, 2021).
Parkinson disease (3 papers, 2018 to 2024). A progressive degenerative disorder of the central nervous system characterized by loss of dopamine producing neurons in the substantia nigra and the presence of Lewy bodies in the substantia nigra and locus coeruleus. "This is particularly relevant given the established link between mitochondrial dysregulation in genetic neuropathies involving mitofusin-1 and Parkinson’s disease associated with parkin." (PMID 39766823, 2024).
sarcopenia (3 papers, 2017 to 2022). Progressive decline in muscle mass due to aging which results in decreased functional capacity of muscles. "Intriguingly, fusion-related proteins (Mfn1/Mfn2) were significantly upregulated in older wild type (WT) mice due to the downregulation of fission protein Fis1, which is consistent with the results obtained in some hip-fractured patients of advanced age with sarcopenia." (PMID 34881083, 2021).
acute myeloid leukemia (2 papers, 2021 to 2022). Acute myeloid leukemia (AML) is a group of neoplasms arising from precursor cells committed to the myeloid cell-line differentiation. "Misexpression of DNM1L and Mfn1/2 may underlie several human hematological malignancies including acute myeloid leukemia (AML), chronic myeloid leukemia (CML), chronic lymphocytic leukemia (CLL) and myelodysplastic syndromes." (PMID 34295888, 2021). "Consistently, time-dependent exposure to doxorubicin, and increased levels of MFN1, MFN2, and OXPHOS in response to doxorubicin, are usually associated with fusion-driven chemoresistance in Jurkat leukemia cells, acute myeloid leukemia (AML), and ovarian cancers." (PMID 36359776, 2022).
autosomal dominant optic atrophy (2 papers, 2023 to 2024). An autosomal dominant hereditary condition characterized by optic atrophy and progressive visual loss. "Mitochondrial dynamics are represented by mitochondrial fission processes controlled by mitofusin 1 (MFN1), MFN2, OPA1 (a gene encoding a dynamin-like mitochondrial GTPase involved in autosomal dominant optic atrophy) and fusion processes regulated by dynamic-related protein 1 (DRP1)." (PMID 37762322, 2023).
Cachexia (2 papers, 2012 to 2021). Severe weight loss, wasting of muscle, loss of appetite, and general debility related to a chronic disease. "The loss of mitochondria is preceded by the reduction in PGC-1α and mitochondrial fusion proteins Mfn1 and 2 during the initial stages of cachexia, while the induction of fission protein FIS1 occurs with the progression of cachexia." (PMID 22769563, 2012). "We report that the expression of both Mfn1 and Mfn2 proteins are repressed during pre-cachexia, and this is one of the earliest alterations in protein expression related to oxidative metabolism we have found in skeletal muscle." (PMID 22769563, 2012). "IL-6 receptor antibody administration after the onset of cachexia improved mitochondrial content, PGC-1α, Mfn1/Mfn2 and FIS1 protein expression." (PMID 22769563, 2012). "Mitochondrial content was not reduced during the initial development of cachexia, while muscle PGC-1α and fusion (Mfn1, Mfn2) protein expression was repressed." (PMID 22769563, 2012).
cardiac ischemia (2 papers, 2024 to 2025). "In contrast, the β2i subunit of the immunoproteasome ameliorates myocardial ischemia/reperfusion injury by regulating Parkin-Mfn1/2-mediated mitochondrial fusion." (PMID 39095788, 2024). "Considering that Hyp treatment in our study upregulated both Mfn1/Mfn2 and Opa1, it is conceivable that strategies aimed at activating mitofusins may complement Opa1-mediated inner membrane fusion to achieve more robust mitochondrial protection in the setting of cardiac ischemia–reperfusion injury." (PMID 40978492, 2025).
cerebral infarction (2 papers, 2022). An ischemic condition of the brain, producing a persistent focal neurological deficit in the area of distribution of the cerebral arteries. "TTC staining showed that Se treatment significantly reduced the cerebral infarction area of MCAO mice, which was increased after knockdown of Mfn1." (PMID 35725978, 2022).